CD4 (CD4 molecule)
Diseases named in the same sentence as CD4 in open-access papers (continued):
Sharing a sentence is not in itself a finding about the gene and the disease.
tumor (continued). "Alternatively, CD8+ T cells, CD4+ Th1 cells, NK cells and B cells help in the detection and elimination of tumour cells through immune surveillance and contribute to tumour elimination." (PMID 40852716, 2025). "Recently, increased expression of TIGIT has been shown on regulatory CD4+ T cells of primary tumor tissue as well as during chronic infections." (PMID 40274631, 2025). "In Module 4, correlations emerged among CD8 GZMK+ cells, CD4 Tm cells, tumor meta-programs related to the cell cycle, and classical and non-classical monocytes." (PMID 40890106, 2025). "MHC class II epitopes have recently been shown to play a major role in antitumoral immune responses in cancer patients, both by enhancing CD8+ T-cell responses and by inducing tumor-targeting CD4+ T cells." (PMID 39741195, 2025). "CD4 cells are also responsible for directing the secretion of cytokines that enable tumor cell infiltration and assist in the creation of memory CD8 T cells." (PMID 39941782, 2025). "Studies have shown the importance of co-stimulation of both CD8+ and CD4 + T-cells for both spontaneous and immunotherapy-triggered anti-tumour immune responses and for circumventing immune tolerance of cancer cells." (PMID 40956795, 2025). "We found that ΔM062R treatment subverted the immunosuppressive properties of TAMs and elevated the avidity of cytokine production in tumor antigen-specific CD4+ T cells." (PMID 40872773, 2025). "In TNBC patients, a higher number of CD8+ T cells and CD4+ T cells infiltrating tumor mass is observed, and the number of B and NK cells is higher than in patients with other BC subtypes." (PMID 40136652, 2025). "This nanoparticle enhances tumor immunotherapy by disrupting mitochondrial function and activating CD4+ and CD8+ T cells, thereby increasing IL-2 and TNF-α expression, and significantly inhibiting tumor growth." (PMID 39742149, 2025). "Generally, tumor-infiltrated CD4+ and CD8+ T cells displayed higher proportions expressing one or multiple activating and inhibitory markers than T cells in the liquid compartments." (PMID 41221283, 2025). "Flow cytometry analysis of CD4+ Tumor-Infiltrating Lymphocytes (TILs) and draining lymph nodes from B16F10 tumor-bearing mice revealed increased IFNγ production in CD4Nlrp3-/- mice compared with control mice at both the mRNA and protein levels." (PMID 40195474, 2025). "As professional antigen-presenting cells, B cells prime CD4+ T cell activation through MHC-II-mediated tumor antigen presentation." (PMID 41246318, 2025). "By boosting CD4+ T-cell activation and antigen presentation, nanoparticles loaded with IL-12 (such as liposomes or hydrogels) trigger a robust anti-tumor immune response." (PMID 40860882, 2025). "Elucidating this metabolic reprogramming will not only shed light on the mechanisms governing T cell fate decisions but also identify strategies to reprogram CD4+ T cell responses in favor of effective anti-tumor immunity." (PMID 40658684, 2025). "The peripheral blood immune cell composition differed significantly from the immune cell composition in the tumor, with more CD4+ T cells and less CD20+ B cells infiltrating SW480 and HCT116 tumors." (PMID 40503011, 2025). "CD4+ T cells expressing TGF-β have long been recognized to negatively impact tumor immunotherapy response." (PMID 40054456, 2025). "HPV-positive tumors exhibit a highly inflamed TME enriched with TILs, including CD8+, CD4+, Treg, and B- cells, particularly in tumor-adjacent regions." (PMID 41254766, 2025). "Next, we conditionally knocked Ltbr into CD4+ T cells (Ltbr-cKI) and assessed its anti-tumor effects, finding that these CD4+ T cells inhibited tumor growth and improved prognosis." (PMID 40436857, 2025). "The consequence of MHCII upregulation on tumor cells is two-fold, which not only benefited the CD4+ T-cell-meditated targeting of tumor cells, but also facilitated the programming of CD4+ T cells with enhanced polyfunctionality and memory potential." (PMID 39885128, 2025).
tumor (continued). "Studies have shown that tumor neoantigens can regulate their fate by promoting the interaction between tumor specific CD4 T cells and tumor specific B cells, thereby enhancing the effector function of CD8 T cells to promote anti-tumor immunity." (PMID 40027134, 2025). "CD4+ T lymphocytes can inhibit tumour growth via immune surveillance, whereas CD8+ T cells are highly enriched in the MASLD microenvironment, contributing to liver inflammation." (PMID 41200753, 2025). "MIBI spatial mapping showed B cells near antigen-presenting cells (CD11c+, CD4+) in Acly-KO tumours." (PMID 40739358, 2025). "The combination treatment reduced interferon-γ expression and increased infiltration of tumor-infiltrating immune lymphocytes, including CD4+ T and CD8+ T cells, into the TME." (PMID 40739089, 2025). "Similar results were obtained for intratumoural infiltration of CD4+ T cells, the percentage of CD3+CD4+ cells in tumor microenvironment significantly elevated to 35.10 %." (PMID 40994623, 2025). "The vaccine induced the accumulation of tumor-specific CD4+ Th cells in the tdLNs, while in the tumors these cells were present and their frequencies were not changed by the vaccine." (PMID 40650228, 2025). "Vaccines can be tailored based on the patient’s tumor mutation profile, using mutation hotspots and predictive algorithms to select candidate neoantigens that effectively activate CD8+ and CD4+ T cells." (PMID 40881694, 2025). "In subgroup analysis, patch/plaque stage MF biopsies showed higher expression of CD5 in CD4 T cells than tumor stage MF biopsies." (PMID 41226451, 2025). "Because malignant cells typically lack surface MHC class II expression, CD4+ T cells can only recognize tumor antigens after cross-priming by autologous DCs." (PMID 41374956, 2025). "In five available paired biopsies, GX-I7 also showed the ability to increase the number of tumour-infiltrating lymphocytes (TILs) of the CD4 and CD8 subtypes." (PMID 40490502, 2025). "After treatment, on day 7, 14, and 21, both the OVV-00 and OVV-01 treatment groups showed an increase in hCD3+ T cells, hCD3+CD8+ T cells, and hCD3+CD4+ T cells in peripheral blood and tumor TILs over time." (PMID 40873562, 2025). "In the case of Rec #8, although induction of neoantigen-specific CD8+ T cells by the short peptide was insufficient, we observed the marked induction of CD4+ T cells by one long peptide that was possibly contributed to drastic tumor shrinkage in this patient." (PMID 40248703, 2025). "CD3+ and CD8+ T cells mainly localize to the peritumoral region, while CD4+ T cells are found within the tumor." (PMID 40868818, 2025). "Subgroup analysis and meta-regression revealed that heterogeneity in CD4+/CD8+ T-cell ratio was influenced by tumor type and concomitant chemotherapy, while heterogeneity in KPS was associated with ICI type." (PMID 41244814, 2025). "CD4+ T-cells play a dual role in cancer immunology, either supporting immune evasion or enhancing anti-tumor immunity, depending on the surrounding cytokine milieu and cellular interactions within the TME." (PMID 40860882, 2025). "We found a significant reduction of CD4+Foxp3+ T cells in the LLC tumor bed of maraviroc-treated mice." (PMID 40553564, 2025). "Pre-immunization against TT enabled recall CD4+ T cell responses targeting tumor cells presenting TT epitopes, achieving significant intratumoral lymphocyte infiltration." (PMID 40661781, 2025). "MSNs can be engineered for the simultaneous delivery of tumor antigens and immune adjuvants, which boosts CD4+ T-cell proliferation." (PMID 40860882, 2025). "The combination of VZV-vax with the tumor-specific E744-62 peptide led to an increase in IFN-γ-producing CD4+ T cells against the VZV gE protein." (PMID 40280970, 2025). "The authors observed that CD4+ T cells from both blood and tumour tissue of all treated patients expressed increased levels of ICOS and produced IFN-γ." (PMID 39325360, 2025).
tumor (continued). "Enhance the effectiveness of immunotherapy by increasing TILs (CD4+, CD8+); reduce exhausted T cells, and improving tumor‐associated macrophage polarization." (PMID 41085102, 2025). "Taken together, these analyses of matched TCRαβ sequences, which are directly clonally related, indicate that cytotoxic CD4+ tumor-infiltrating lymphocytes (TILs) from tumors communicate with the circulation." (PMID 40299576, 2025). "Subsequently, they are reintroduced into the patient's body where they migrate to the CD8 + and CD4 + T cells to initiate anti-tumor immunity." (PMID 39179939, 2025). "Sustained pro-inflammatory cytokine production (notably IL-6, TNF-α, and IL-2R) induces CD4+ T-cell exhaustion and accelerates tumor progression." (PMID 40969752, 2025). "The high-risk group exhibited significantly greater infiltration of regulatory T cells (Tregs, CD4 + Foxp3+), indicative of an immunosuppressive tumor microenvironment." (PMID 40533802, 2025). "As an extension, IFN-γ and TNF-α neutralization resulted in a reduction of CD4+Foxp3+ Tregs in the LLC tumor bed compared with IgG-treated mice." (PMID 40553564, 2025). "In HRD cancers, the JAK-STAT pathway is upregulated in tumor cells, CD4+/CD8+ T cells, and macrophages, implying a common upstream effector in this pathway within HRD cancers." (PMID 40830526, 2025). "In the TME, CD8+ T cells and CD4+ T cells are two important subgroups of T cells that are essential for anti‐tumour immunity." (PMID 40579785, 2025). "Our results showed that HO-1 inhibition significantly increased CD4+ T cell infiltration in the tumor tissues of the combined treatment group in WT-RM-1-parent mice, compared to each treatment alone and the control group (P < 0.05)." (PMID 40037158, 2025). "It is important to note that CD4-positive lymphocytes play a multifaceted role in the anti-tumor immune response, since CD4 marker is also expressed in regulatory T cells with immunosuppressive characteristics, a phenomenon also observed after ECT." (PMID 40007542, 2025). "Most MDV-transformed tumor cells are CD4+ T cells, resulting from an (oligo)clonal expansion of transformed CD4+ T cells." (PMID 41013577, 2025). "This phenomenon was particularly pronounced in tumor tissues, especially in CD4+ and CD8+ T-cell subsets." (PMID 40299475, 2025). "These epitopes are typically presented on the surface of tumor cells via MHC class I (for CD8+ T cells) or class II (for CD4+ T cells) molecules." (PMID 41374974, 2025). "Further studies are needed to explore novel strategies using these combinations, since epigenetic mechanisms can influence both tumor cells and immune cells, including CD4, CD8, and regulatory T-cells." (PMID 40805133, 2025). "CCL5 is involved in the recruitment of immune cells such as CD8+ T cells, CD4+ T cells, and M1 macrophages, enhancing anti-tumor immunity." (PMID 40777006, 2025). "In the context of adoptive cell transfer immunotherapy, B cells have been shown to cooperate with CD4+ T helper cells and dendritic cells to achieve durable anti-tumor responses through cytokine production and antigen presentation, respectively." (PMID 41066027, 2025). "Low glucose also induces the expression of the transcription factor forkhead box P3 (FoxP3), which converts anti-tumor CD4+ effector T cells (Teff) cells into pro-tumor regulatory T cells (Treg)." (PMID 39796781, 2025). "Cell abundance analysis revealed significant enrichment of proliferating lymphocytes (ProL) and IgL-expressing plasma cells (IgL-Plasma) in the tumor group, while the proportion of CD4+ T cells (CD4T) was notably decreased." (PMID 39944086, 2025). "These cytotoxic CD4+ T cells are capable of directly lysing tumor cells by recognizing antigens presented onMHC class II molecules expressed by tumor cells." (PMID 40361239, 2025).
tumor (continued). "As for tumour–adjacent bowel, CD4+ Treg cells were increased in lamina propria, when several T cell and B cell subtypes were increased in muscularis propria, such as CD4+ Tcm, CD4+ Tem, CD4+ Treg, CD8+ Tem, naïve B cell and memory B cells." (PMID 39934971, 2025). "Chrysin efficiently inhibits tumor growth and boosts anti-tumor immunity in mice, demonstrated by a higher proportion of CD4+ and CD8+ T cells within tumor tissues in the H22 xenograft model." (PMID 41515954, 2025). "An intriguing phenomenon is that the loss of IFN-γ signaling (e.g., due to mutations in the JAK1 gene) leads to the inability to induce MHC class II expression on tumor cells, thus preventing their recognition and elimination by CD4+ CTLs." (PMID 40725022, 2025). "Previous studies mainly focused on its anti-tumor activities through facilitating the anti-tumor immune responses by increasing immune cell infiltration of CD4+ and CD8+ T-cells." (PMID 39900908, 2025). "CD4+Foxp3+ Treg cell frequencies were substantially reduced in all peripheral lymphoid organs analyzed as well as in the tumor, whereas CD4+Foxp3- conventional T cell frequencies were only slightly reduced in draining (dLN) and control lymph nodes (cLN)." (PMID 40977681, 2025). "That suggested the superior tumor suppression was brought about by antigen-specific CD8+ CTLs enhanced by CD4+ T cell help from the E743–77-pulsed bm12 mBMDC vaccine." (PMID 40857404, 2025). "Second, our focus was on major immune and tumour cell types, such as CD8+ T cells, CD4+ T cells, B cells and tumour cells." (PMID 40842484, 2025). "In conclusion, high FOXP3‐positive cell density or FOXP3+/CD4+ cell ratio around the tumor correlated with a worse response to BCG treatment for bladder CIS." (PMID 40084633, 2025). "To determine the role of CD4+ T cells in calcipotriol-mediated antitumor effects, we also injected a subgroup of calcipotriol-treated WT mice with anti-CD4 Ab starting 1 day before tumor cell implantation." (PMID 39782693, 2025). "Meanwhile, B cells can capture tumor-associated antigens via the B cell receptor (BCR), and after internalization and processing, present them to CD4+ and CD8+ T cells to exert antitumor immune effects." (PMID 40255404, 2025). "IL1R1 was positively correlated with regulating T cells CD4 and macrophages M2, implying that IL-1 signaling regulated tumor microenvironmental homeostasis and immune response through different immune cells." (PMID 40535567, 2025). "The generation and expansion of CD4+ T cells depend on signaling molecules derived from the tumor and complex interactions with other immune cells." (PMID 40027151, 2025). "This interaction activates the STAT3 signaling pathway, upregulating immunosuppressive molecules such as FOXP3, CD39, and IL‐10, while promoting the recruitment of peripheral Tregs to tumor sites and facilitating the conversion of CD4+ T cells into Tregs." (PMID 41201063, 2025). "This contrasts to total CD4+ T-cells and FoxP3+ Tregs, both of which were highest in the 10–20 μm category, thus residing further away from tumour cells compared to total CD8+ T-cells." (PMID 41310655, 2025). "Conversely, the utility of RGB has been shown to selectively suppress the differentiation of CD4+Foxp3+ Treg cells, thereby inhibiting tumor growth." (PMID 40297580, 2025). "Overall, tumor-infiltrating CD4+ T cells play an essential role in immunotherapy, comparable to that of CD8+ T cells." (PMID 41008548, 2025). "In these patients specifically, high CD4+ T cell infiltration was also observed, suggesting a correlation between activin and tumor immune response." (PMID 41463203, 2025). "In the tumor microenvironment, those involved in immune surveillance are CD4+ T helper (Th) cells, CD8+ cells, natural killer (NK) cells, and some neutrophils." (PMID 40191727, 2025).
tumor (continued). "NHL, predominantly that of B-cell origin, is often characterized by an immunosuppressive tumor microenvironment driven by intratumoral CD4+CD25+ Tregs that inhibit effector T cell infiltration." (PMID 40723175, 2025). "This can sensitize tumor cells to immune activation and trigger co-stimulation of CD4+ and CD8+ T cells." (PMID 41345386, 2025). "Collectively, these results indicate that RCOR2 promotes tumor growth through reducing infiltration of CD4+ and CD8+ T cells." (PMID 40608411, 2025). "We also assessed the efficacy of T4G828zT2 T cells in an HCC PDX model and found thar the tumor sizes of the T4G828zT2 group were smaller than those of mice that were infused with CD3+ G28zT2 T cells or CD4+ T28zT2 T cells." (PMID 40107245, 2025). "In contrast, immune cells, including NK cells, cytotoxic CD8+ T cells, and pro-inflammatory Th1 CD4+ T cells, respond to tumor growth by blocking pro-tumor effects." (PMID 40869156, 2025). "While our study focuses on class-I ncTSA prediction, we point out that NovumRNA also predicts class-II ncTSAs, which are crucial for the recognition of tumor cells by CD4+ T cells." (PMID 41031372, 2025). "T lymphocytes, particularly cytotoxic CD8+ and helper CD4+ T cells, are central orchestrators of effective anti-tumor immunity." (PMID 41294574, 2025). "The cell types included natural killer (NK) cells, CD4+ and CD8+ T cells, Tregs, proliferating T cells, dendritic cells (DCs), antigen-presenting cells (APCs), tumor-associated neutrophils (TANs), and two clusters of TAMs." (PMID 40917508, 2025). "The increased CD4+ T cells provide helper functions, facilitating the recognition and killing of tumor cells by CD8+ T cells and NK cells." (PMID 40264767, 2025). "The importance of MVI, tumor capsule integrity, and CD4+ T cell density in predicting early postoperative recurrence is emphasized." (PMID 41212769, 2025). "Immunofluorescence staining for T cell markers CD3 and CD8, as well as T helper cell markers CD3 and CD4, was performed on tumor sections from saline-, NRG-, PTT-, and PTT/NRG-treated groups." (PMID 41438076, 2025). "Treatment with P-NT-aPD1 also increased the proportion of tumor-infiltrating CD4+ and CD8+ T cells and decreased the percentage of PD-L1-expressing non-immune cells after 25 days." (PMID 41294574, 2025). "CD4+ T cells play an indispensable role in anti-tumour immune responses, making them particularly significant in tumour immunology and immunotherapy." (PMID 40852716, 2025). "They deliver tumor-specific antigens along with adjuvant agents to stimulate DC activation, leading to the expansion of tumor-directed CD4+ T cells and cytotoxic lymphocytes." (PMID 41097726, 2025). "Recent findings showed that cryptic peptides encoded from circRNAs can stimulate a CD4 + and CD8 + T cell-mediated anti-tumor immunity." (PMID 39980011, 2025). "This implies that in the tumor microenvironment, not only does spermidine interfere with immune cell function but also abnormally elevated arginine itself acts as a barrier to CD4+ T cell infiltration." (PMID 41304979, 2025). "Knockdown of RFWD3 inhibited proliferation and increased secretion of IFN‐β at the cellular level, and repressed tumor growth with an increase in CD4+, CD8+, Granzyme B+/CD8+, IFN‐γ/CD8+, NK, and DC cells and a decrease in MDSCs." (PMID 41117130, 2025). "CD4+CD25+ Tregs competitively suppress the immune response to tumor cells by binding the IL-2 high affinity receptor to IL-2, and IL-2 is one of the cytokines of the primary stimulatory production of Teff." (PMID 40216744, 2025). "As expected, tumor size decreased in CD4-Cre PRR cKO mice following the transfer of iNKT cells, whereas the frequency of the IFN-γ+ population in CD4 and CD8 T cells remained unchanged." (PMID 41451235, 2025).